EGFR (epidermal growth factor receptor)
Diseases named in the same sentence as EGFR in open-access papers (continued):
Sharing a sentence is not in itself a finding about the gene and the disease.
lung cancer (continued). "EGFR-TKIs were the first molecular-targeted drugs to dramatically change the chemotherapeutic approach to lung cancer." (PMID 27270313, 2016). "MiR-133b expression was found to be reduced in lung cancer tissue, and was shown to regulate cell growth, invasion, and apoptosis via regulation of EGFR expression." (PMID 27575252, 2016). "In the present study, we established an in vivo imaging model for LMC with an EGFR-TKI sensitive EGFR-mutant lung cancer cell lines." (PMID 26716903, 2016). "The clinical success of EGFR inhibitors in patients with lung cancer is limited by the inevitable development of treatment resistance." (PMID 27447558, 2016). "KDM5A was shown to be a powerful mediator of drug tolerance to gefitinib, a small molecule inhibitor of the epidermal growth factor receptor (EGFR), in the EGFR-mutant lung cancer cell line PC9." (PMID 27224921, 2016). "The sensitivity of 35 cases of surgically resected lung cancer to erlotinib was examined using SDI or CD-DST, and compared with EGFR mutation status." (PMID 27070423, 2016). "Therapeutic effect of our synthetic fc-rPEI-Cdots/pooled siRNA (cyclin B1 plus EGFR) and fc-rPEI-Cdots/single siRNA (cyclin B1) nanoagents was examined by measuring viability of lung cancer cells after treatment." (PMID 26880047, 2016). "We notice that around 9.8% of wt-EGFR patients showing partial regression of lung cancer, and another 52% stable disease." (PMID 26646697, 2016). "Cell-free DNA sequencing libraries from four lung cancer patients (LC1, LC3, LC4, and LC10) with EGFR T790M mutations and one healthy control (C5) were selected for serial fraction collection." (PMID 27428049, 2016). "Here, we analyzed the mutational frequency of EGFR and KRAS gene, as well as EML4-ALK rearrangement, and summarized the clinicopathological characters of Chinese lung cancer patients." (PMID 26739511, 2016). "The protein forms a complex with MALT1, which in turn has recently shown to be required for EGFR-induced NF-κB activation and to contribute to EGFR-driven lung cancer progression." (PMID 27279498, 2016). "Increased Akt activation is one mechanism through which lung cancer cells develop resistance towards EGFR TKIs." (PMID 27458163, 2016). "Drug resistance to tyrosine kinase inhibitor (TKI) is the main obstacle for efficient treatment of epidermal growth factor receptor (EGFR)-mutant lung cancer patients." (PMID 27151505, 2016). "Among the 19 cases of EGFR mutant lung cancer that were identified, we observed variation in VDR expression and cell morphology." (PMID 26654942, 2016). "This approach also revealed differential drug-induced tyrosine phosphoproteome responses between naïve and drug-resistant EGFR mutant lung cancer cells to EGFR tyrosine kinase inhibitor." (PMID 28154798, 2016). "In summary, our data demonstrated a theoretical model of SREBP inhibition enhance therapeutic response of lung cancer cells to EGFR-TKI gefitinib." (PMID 27447558, 2016). "In China alone, ∼40,000 new cases per year of EGFR (L858R)-positive lung cancer patients are expected to be diagnosed that express one of these HLA allotypes." (PMID 28123873, 2016). "The recent discovery of driver mutations, such as epidermal growth factor receptor (EGFR) mutations and anaplastic lymphoma kinase (ALK) rearrangements, has dramatically changed the treatment of lung cancer." (PMID 27518729, 2016). "The epidermal growth factor (EGF) receptor is associated with the development of lung cancer, and approximately 14% of NSCLCs harbour mutations in the EGF receptor (EGFR)." (PMID 27449083, 2016). "Epidemiologic studies implicate vitamin D status as a factor that influences growth of EGFR mutant lung cancers." (PMID 26654942, 2016). "The EGFR mutant T790M, found in lung cancers with very high prevalence, can circumvent suppression by TKIs." (PMID 26745678, 2016). "The expressions of CDH5 mRNA and protein were detected in mutant and wild type EGFR genes transfected stable lung cancer cells." (PMID 27362942, 2016).
lung cancer (continued). "Though certain targeted therapies such as anti-EGFR are in clinical practice, they have shown limited success in lung cancer patients who are smokers." (PMID 27542207, 2016). "Rebiopsy is highly recommended to identify the mechanism of acquired resistance to EGFR-TKIs in advanced lung cancer." (PMID 26850068, 2016). "MET amplification has been reported to induce gefitinib resistance via ErbB3 in EGFR mutant lung cancers." (PMID 26919104, 2016). "This suggested that overexpressed wt-EGFR mimicked mutant EGFRs seen in lung cancer patients, which are less responsive to EGF stimulation mediated downregulation." (PMID 26646697, 2016). "Several third-generation EGFR TKIs, which irreversibly block T790M mutant EGFR, have shown to be effective in patients with acquired EGFR mutant lung cancer patients who acquired T790M after treatment failure with previous EGFR TKIs." (PMID 26862733, 2016). "Till date, we have only limited data concerning evaluation of driver mutations incidence (especially EGFR and KRAS genes) in CNS metastases of lung cancer." (PMID 25902737, 2016). "Unfortunately, despite great progress in the treatment of lung cancer, resistance to EGFR-TKIs commonly occurs, leading to a modest response rate to first-line TKI therapy or to frequent recurrence after temporarily effective TKI treatment." (PMID 26745678, 2016). "Our transgenic mouse model data confirmed that wt-EGFR-driven lung cancers were dependent on continuous expression of wt-EGFR for maintenance." (PMID 26646697, 2016). "To validate the analysis of lncRNAs profiles, we assessed the mRNA expression of BC087858 by qRT-PCR in different lung cancer cell lines and tissues from patients before EGFR TKIs treatment (BT group) and after harboring acquired resistance to TKIs (AR group)." (PMID 27409677, 2016). "The well-studied gene related to lung cancer, EGFR gene, was identified by these two searching strategies using PPI network." (PMID 28117655, 2016). "Few data have been provided so far concerning the roles of Notch1 in lung adenocarcinoma harboring mutations in other lung cancer driver genes, such as PIK3CA or EGFR (Epidermal Growth Factor Receptor)." (PMID 27847554, 2016). "Like the MET signaling pathway, which is also aberrantly activated in lung cancer, the PI3K/AKT pathway is strongly activated and plays a very important role in lung cancer development as well as EGFR-TKI resistance." (PMID 27494877, 2016). "For example, patients with EGFR mutant adenocarcinoma lung cancer (a type of NSCLC) treated with EGFR-TKI have been reported to achieve long-term survival while maintaining good performance status." (PMID 27542716, 2016). "HNPs were modified with antibody specific to cancer biomarker epidermal growth factor receptor, then applied to human lung cancer (A549) and mouse hepatocyte cells (AML12), and in vitro PTT effect was studied." (PMID 27877887, 2016). "Currently, this acquired resistance is the greatest challenge for EGFR-TKI treatment of lung cancer." (PMID 27825114, 2016). "Receptor tyrosine kinase inhibitors, such as EGFR inhibitors, have been reported to induce a cytoprotective response in lung cancer cells." (PMID 27029060, 2016). "Together with previous studies, our study further addresses the critical role of mutant EGFR genes in the promotion of angiogenesis in lung cancer cells." (PMID 27362942, 2016). "We also show that hyperthermic chemotherapy is highly effective in killing mutant EGFR-driven lung cancer cells." (PMID 26654941, 2016). "In our MIIP-overexpressing lung cancer cells, EGFR level decreased as early as the appearance of the semiglycosylated 160-kD EGFR peptides." (PMID 26824318, 2016). "Epidermal growth factors receptor (EGFR) common mutations first and anaplastic lymphoma kinase (ALK) translocations later led new insights in lung cancer biology knowledge." (PMID 27433281, 2016).
lung cancer (continued). "Although DNA copy number abundance of EGFR and ERBB2 had been studied independently, the associations between EGFR-activating mutations, whole ErbB family, and clinical prognosis in lung cancer were still needed to be investigated." (PMID 26824984, 2016). "In our study, increased phosphorylation of EGFR Y1068 was observed in exon 19 deletion stable lung cancer cells, which is similar to previous reports in lung cancer cells." (PMID 27362942, 2016). "Our preceding study showed that EGFR ctDNA levels reflected the effect of EGFR-TKI in EGFR-mutant lung cancer, i.e. the amount of EGFR ctDNA decreased in response to EGFR-TKI treatment reflecting the radiologic responses at least in part." (PMID 27708242, 2016). "In conclusion, Rg3 inhibits EMT and invasion of lung cancer by down-regulating FUT4 mediated EGFR inactivation and blocking MAPK and NF-κB signal pathways." (PMID 26636541, 2016). "CDH5, which is upregulated in exon 19 deletion mutant EGFR gene overexpressed lung cancer cells, is related to the ability of metastasis in lung cancer cells." (PMID 27362942, 2016). "Our work clearly shows that IPHC-CT is effective against lung cancer patients harboring mutant EGFR." (PMID 26654941, 2016). "Taken together, our study is the first to indicate the potential role of YAP1 as a common modulator of resistance mechanisms and a potential novel, actionable target that can improve responses to platinum, radiation and EGFR-targeted therapy in lung cancer." (PMID 26716514, 2016). "Treatment with AT-101 in combination with gefitinib significantly inhibited cell proliferation, as well as promoted apoptosis of EGFR TKIs resistant lung cancer cells." (PMID 27431492, 2016). "Our previous study indicated that upregulation of cIAP2 by E6 oncoprotein via EGFR/PI3K/AKT pathway confers cisplatin resistance in HPV-infected lung cancer." (PMID 27083050, 2016). "Given the central role played by AKT kinase in the EGFR pathway in lung cancer, both total AKT levels and its Ser473-phosphorylated form were also measured." (PMID 27449083, 2016). "In the present study we investigated the effect of PD 0332991 in EGFR-TKI-resistant lung cancer cells, both in vitro and in vivo." (PMID 27825114, 2016). "Among lung cancer biomarkers, EGFR and KRAS are the most frequently mutated genes in lung cancer patients and have been routinely used as biomarkers for a decade." (PMID 27999344, 2016). "For example, the discovery of activating mutations in the epidermal growth factor receptor (EGFR) helped explain the success of EGFR inhibitors in a subset of lung cancer patients, in the process revolutionizing the screening and treatment of these patients." (PMID 27738492, 2016). "CAR10 binds to and stabilizes TF Y-box-binding protein 1 (YB-1), leading to up-regulation of EGFR and proliferation of lung cancer cells." (PMID 27397102, 2016). "Here, we developed the cetuximab-capped MP-SiO2 NP as the drug carrier to specifically target EGFR-mutant lung cancer cells and efficiently release loaded drugs including doxorubicin and gefitinib." (PMID 27151505, 2016). "To further validate the inhibitory effect of miR‐134 on EGFR expression in lung cancer cells, we transfected four additional NSCLC cell lines, H460, H520, H1975 and PC9, with miR‐134 mimics." (PMID 27241841, 2016). "Increased fluorine-18-flurodeoxyglucose (FDG) uptake in lung cancers has been shown to be a prognostic factor for NSCLC patients, and lower SUV has been reported to be associated with favorable outcomes in EGFR targeted therapy." (PMID 26979333, 2016). "As KDM5A was shown to mediate drug tolerance, we investigated the ability of YUKA1 to prevent drug tolerance in EGFR-mutant lung cancer cells treated with gefitinib and HER2+ breast cancer cells treated with trastuzumab." (PMID 27224921, 2016).
lung cancer (continued). "The content of mutant EGFR DNA in lung cancer tissues was determined using an Amplification Refractory Mutation System." (PMID 27368002, 2016). "CAR10 bound and stabilized transcription factor Y-box-binding protein 1 (YB-1), leading to up-regulation of the epidermal growth factor receptor (EGFR) and proliferation of lung cancer cells." (PMID 27322209, 2016). "For most patients with advanced lung cancer harboring wild-type EGFR, chemotherapy is the prior choice." (PMID 26919104, 2016). "Taken together, our findings suggest that miR‐134 inhibits non‐small cell lung cancer growth by targeting the EGFR." (PMID 27241841, 2016). "Adenocarcinoma patients with an EGFR mutation have a longer progression-free survival after treatment with the EGFR-TKI, gefitinib, as compared to standard chemotherapy, making targeted therapy a hallmark of lung cancer treatment." (PMID 27825114, 2016). "Here, we clearly showed that AZD9291 has potential against EGFR-TKI naïve LMC of EGFR-mutant lung cancer cells." (PMID 26716903, 2016). "Epidermal growth factor receptor (EGFR) inhibitors such as erlotinib are novel effective agents in the treatment of EGFR-driven lung cancer, but their clinical impact is often impaired by acquired drug resistance through the secondary T790M EGFR mutation." (PMID 27721983, 2016). "For example, miR‐133a can inhibit cell proliferation and invasiveness through directly suppressing the expressions of insulin‐like growth factor 1 receptor, TGF‐beta receptor type‐1, EGFR in non‐small cell lung cancer 21, and breast cancer." (PMID 27465833, 2016). "The present studies were conducted to address the potential association of DUOX1 silencing in lung cancer, with development of EMT and EGFR TKI resistance." (PMID 27694834, 2016). "Lung cancer patients with high-expression of wt-EGFR showed longer Overall Survival in comparison to low-expression patients after TKI treatment." (PMID 26646697, 2016). "For example, the combination of a SRC inhibitor and an EGFR inhibitor synergistically enhanced apoptosis in EGFR-dependent lung cancer cells." (PMID 27438149, 2016). "EMT initiating events including β-catenin nuclear translocation have recently been shown to be essential for the growth of EGFR mutant lung cancers." (PMID 26654942, 2016). "Among 1,386 patients who were diagnosed with lung cancer between December 2010 and December 2013, we identified 511 patients with advanced NSCLC who were screened for EGFR mutations." (PMID 26894507, 2016). "Although EGFR TKI has undoubtedly revolutionized the treatment of EGFR-mutant lung cancer patients, but more investigation is necessary to elucidate mechanisms of primary resistance to EGFR TKI." (PMID 27121209, 2016). "EBUS-TBNA is useful not only for proper staging and diagnosis of lung cancer, but also to obtain samples for mutation analysis of NSCLC after EGFR-TKI, as demonstrated in this study." (PMID 27457475, 2016). "Significantly increased HUVEC cells were observed in the group co-cultured with A549 stable lung cancer cells transfected with exon 19 deletion mutant EGFR gene." (PMID 27362942, 2016). "Thus, our findings suggest that the EGFR inhibitors may potentially facilitate anti-tumor adaptive immune responses by breaking tolerance especially in lung cancers with sensitizing EGFR mutations or EGFR overexpression that are associated with over-expression of PD-L1." (PMID 27467256, 2016). "In conclusion, IL10 and EGFR regulate each other through positive feedback, which leads to lung cancer formation." (PMID 26956044, 2016). "A variety of agents that target EGFR (epidermal growth factor receptor), ALK (anaplastic lymphoma kinase), or ROS1 (c-ros oncogene 1) have improved the outcome of lung cancer patients bearing specific driver mutations." (PMID 27835880, 2016).
lung cancer (continued). "Although the role of EGFR signaling in the pathogenesis and progression of NSCLC is well recognized, the importance of Notch pathway and its correlation with EGFR in lung cancer is still under investigation." (PMID 27770511, 2016). "It was reported recently that EGFR expression is regulated by SMARCE1, SMARCA4, and ARID1A and that SMARCE1 deficiency confers TKI resistance in lung cancer." (PMID 27783942, 2016). "Mutant-selective, 3rd-generation EGFR-TKIs were recently developed to control lung cancer cells harboring T790M-mediated resistance." (PMID 26980747, 2016). "The Axl receptor tyrosine kinase (RTK) has been shown to modulate acquired resistance to EGFR-targeted therapies in both breast and lung cancers." (PMID 27775700, 2016). "Present results in HNSCC, together with previous results in lung cancer models, point to AvidinOX as a wide applicable tool for making low doses of anti-EGFR antibodies effective against cancer." (PMID 26575422, 2016). "On the other hand, Src has been previously reported to induce TKI resistance in EGFR mutant lung cancer by inducing EMT and cancer metastasis." (PMID 27419630, 2016). "In the present study, we showed that gefitinib modestly inhibited cell viability of lung cancer cell lines, H358 and A549, through inhibition of EGFR phosphorylation and the downstream signaling molecules, Akt and ERK1/2." (PMID 26919104, 2016). "Although AKT isoforms are only mutated in a small percentage of human lung cancers, AKT signaling is downstream of a number of oncogenes including PI3K, EGFR and HER2/EGFR2." (PMID 26654940, 2016). "The epidermal growth factor receptor (EGFR)-mutant-lung cancer represents 10% and 25% of non-small-cell lung cancers (NSCLC) in Caucasians and East Asians, respectively." (PMID 26716903, 2016). "This was noted in studies of MET amplified lung cancer cells, which demonstrated that the formation of EGFR:MET and ErbB2:MET heterodimers rendered the EGFR family member resistant to dephosphorylation in the presence of their respective TKI." (PMID 27597943, 2016). "A549 lung cancer cells were retrovirally transfected with vectors containing wild type and mutant EGFR genes (exon 19 E746-A750 deletion and exon 21 L858R missense mutations) as described in the material and method section." (PMID 27362942, 2016). "The results of their studies should help us improve the clinical efficacy of EGFR-TKIs in the treatment of EGFR-mutant lung cancers by delaying the emergence of drug resistance." (PMID 27270313, 2016). "Lung cancer patients subjected to the EGFR tyrosine kinase inhibitor (EGFR-TKI) treatment were prospectively collected, and ctDNA levels represented by the activating and T790M mutations were measured." (PMID 27934896, 2016). "Our data provides rationale for potential combinations of erlotinib and immunotherapies for the treatment of lung carcinomas in the early setting, before the establishment of tumor relapse with long-term EGFR inhibition." (PMID 27685624, 2016). "The epidermal growth factor receptor (EGFR) has been broadly explored as a drug target for treatment, since it is overexpressed in various tumors, such as breast and lung carcinomas." (PMID 27790245, 2016). "MiR-128b directly targets EGFR, and its expression is positively correlated with clinical response and survival for Gefitinib treatment in lung cancer." (PMID 27790245, 2016). "The data presented here thus provide rationale for potential combinations of erlotinib and immunotherapies for the treatment of lung carcinomas in the early setting, before the establishment of tumor relapse with long-term treatment with an EGFR-TKI." (PMID 27685624, 2016). "In this paper, we summarize the emerging role of miRNAs as regulators to modulate the EGFR signaling and the resistance of lung cancer cells to anti-EGFR therapy." (PMID 26273639, 2015).